CREBBP (CREB binding lysine acetyltransferase )
Diseases named in the same sentence as CREBBP in open-access papers (continued):
Sharing a sentence is not in itself a finding about the gene and the disease.
bone tumors (3 papers, 2012 to 2023). "In bone tumors, the MSKCC cohort had significantly fewer mutations in MAP3K1, CREBBP, MCL1, GNAQ, MEF2B, MYCN, SDHA, and SMARCA4." (PMID 37546405, 2023). "In bone cancer, mutations of CREBBP have been reported in NGS studies, but its role has not been fully investigated yet." (PMID 37373240, 2023). "High-level amplification of TGFβ2 (1q41), CCND3 (6p21), WI-6509 (11qtel), SHGC-5557 (12ptel), TCL1A (14q32.1), CREBBP (16q13.3), HIC1 (17p13.3), THRA (17q11.2), AFM217YD10 (17qtel), LAMA3 (18q11.2), RUNX1 (21q22.3) and D22S543 (22q11), was commonly observed in aggressive bone tumors." (PMID 23199169, 2012).
breast tumor (3 papers, 2006 to 2022). "Protein expression of CREBBP was detected at a medium level in both normal breast and breast tumor tissues." (PMID 36114448, 2022). "CREBBP, EP300, ESR1, GATA3, and MYC are well-known genetic biomarkers and mutate frequently in breast tumors." (PMID 34235216, 2021). "We found that with the optimal two-gene classifier (SIRT1, CREBBP) about 80% of these independent breast tumour samples could be correctly classified." (PMID 16638127, 2006).
epilepsy (3 papers, 2014 to 2023). A brain disorder characterized by episodes of abnormally increased neuronal discharge resulting in transient episodes of sensory or motor neurological dysfunction, or psychic dysfunction. "In the present study, CREBBP has emerged as one of the central hub genes of the generated epilepsy PPI network." (PMID 36982355, 2023). "A total of 33 children underwent preoperative genetic whole‐exome testing, and 4 of them had pathogenic genes related to epilepsy, including CACNA1A, CREBBP, MTOR, and NPRL2." (PMID 37786975, 2023). "Not surprisingly, REST and CREBBP are both prominently present in the epilepsy PPI network generated here." (PMID 36982355, 2023). "Not surprisingly, mounting evidence implicates CREBBP in multiple physiological processes, such as cell cycle regulation, neuroplasticity, learning, memory and, more recently, epilepsy." (PMID 36982355, 2023).
Menke-Hennekam syndrome (3 papers, 2022 to 2025). "Menke-Hennekam syndrome (MKHK) is a recently described rare autosomal dominant disorder caused by loss-of-function variants in exon 30 or 31 of CREBBP (CREB-binding protein) or EP300 genes." (PMID 40860344, 2025). "Menke-Hennekam syndrome consists of at least three domain/region-specific subtypes within the genes CREBBP and EP300 (MKHK-ZZ, MKHK-TAZ2, and MKHK-ID4)." (PMID 38553851, 2024). "Subsequently, individuals carrying these variants were established as having an entity distinct from RSTS, recently described as Menke-Hennekam syndrome (MKHK1 and MKHK2; OMIM: 618332 and 618333, for variants in CREBBP and EP300, respectively)." (PMID 38553851, 2024).
osteosarcoma (3 papers, 2020 to 2024). A usually aggressive malignant bone-forming mesenchymal neoplasm, predominantly affecting adolescents and young adults. "In an in vitro and animal model, BMSC-EVs carried the non-coding RNA activated by DNA damage (NORAD) into osteosarcoma cells and upregulated CREB-binding protein (CREBBP) by sponging miR-877-3p to promote proliferation, invasion, migration, and angiogenesis." (PMID 38392967, 2024).
schizophrenia (3 papers, 2021 to 2023). A major psychotic disorder characterized by abnormalities in the perception or expression of reality. "Therefore, the current insight that CREBBP is upregulated in patients with schizophrenia may not be a solid theory and further studies are required." (PMID 37520228, 2023).
adenoid cystic carcinoma (2 papers, 2014 to 2022). A malignant tumor arising from the epithelial cells. "TCGA material reported a pathogenetic or unknown variant rate of only 2% for IDCs, but in rare adenoid cystic carcinomas of the breast, 31% of tumours have shown CREBBP pathogenetic or unknown variants." (PMID 36085291, 2022).
angioimmunoblastic T-cell lymphoma (2 papers, 2023 to 2025). A mature T-cell non-Hodgkin lymphoma, characterized by systemic disease and a polymorphous infiltrate involving lymph nodes and extranodal sites. "Mutations in the CREBBP/EP300 gene are also often identified in other types of lymphomas besides DLBCL, including FL, in situ follicular neoplasia, peripheral T-cell lymphoma (PTCL), angioimmunoblastic T-cell lymphoma (AITL), and plasmablastic lymphoma." (PMID 40426926, 2025).
Arrhythmia (2 papers, 2024 to 2026). Any cardiac rhythm other than the normal sinus rhythm. "A previous study shows that CREBBP is associated with the left atrial diameter and arrhythmia recurrence after AF catheter ablation via the calcium signaling pathway." (PMID 39742001, 2024). "In parallel, 902 arrhythmia-related genes were retrieved, yielding 24 overlapping targets, among which five hub genes (PIK3CA, CREBBP, NR3C1, SCN10A, and KCNA5) were identified." (PMID 42292832, 2026).
chronic myeloid leukemia (2 papers, 2015 to 2018). "Our results show that the GATA1/MYC axis is as a key component of EP300/CREBBP bromodomain inhibitors mechanism of action in chronic myeloid leukemia (CML) cell line K562." (PMID 29884215, 2018).
colon adenocarcinoma (2 papers, 2021 to 2023). "Analyzing The Cancer Genome Atlas (TCGA), we found significantly lower CREBBP and EP300 expression in tumors of patients with colon adenocarcinoma (COAD) and rectum adenocarcinoma (READ) compared with matched nonmalignant tissues." (PMID 34258881, 2021).
developmental delay (2 papers, 2023 to 2025). "The main features of MKHK1 caused by CREBBP mutations include developmental delay, distinctive facial features, autistic behavior, feeding difficulties, recurrent upper airway infections, and brain abnormalities revealed by MRI." (PMID 36797748, 2023).
endometriosis (2 papers, 2013 to 2014). The growth of functional endometrial tissue in anatomic sites outside the uterine body. "CREBBP was also central in one of our miRNA regulated pathway networks associated with angiogenesis in endometriosis." (PMID 24927773, 2014). "Decreased miR-20a and miR-200b may contribute to the up-regulation of CREB binding protein (CREBBP) mRNAs in endometriosis." (PMID 24927773, 2014).
gastric adenocarcinoma (2 papers, 2021 to 2025). "In an additional analysis of 55 WES gastric adenocarcinomas from patients treated with anti–PD-1 therapy in the second- or third-line setting, only six cases harbored coding mutations in CREBBP and/or EP300." (PMID 41301688, 2025). "A loss‐of‐function mutation in the CBP/CREBBP gene, which encodes a HAT, is common to many cancers, including GC, and MAP2K4 loss of expression has been reported in gastric adenocarcinoma associated with poor survival." (PMID 33724653, 2021). "Subgroups with high TMB and MSI scores are significantly enriched for mutant samples in CREBBP and/or EP300, especially in GEJ and gastric adenocarcinomas (>30%) and esophageal adenocarcinomas (16%), compared to TMB-Low and MSS groups (3–4%)." (PMID 41301688, 2025).
Huntington disease (2 papers, 2023 to 2025). Huntington disease (HD) is a rare neurodegenerative disorder of the central nervous system characterized by unwanted choreatic movements, behavioral and psychiatric disturbances and dementia. "Histone deacetylase inhibitors, which can indirectly modulate CREBBP activity, have been explored for their neuroprotective effects, as observed in models of Huntington’s disease." (PMID 38002524, 2023).
idiopathic pulmonary fibrosis (2 papers, 2021 to 2022). Idiopathic pulmonary fibrosis (IPF) is a nonneoplastic pulmonary disease that is characterized by the formation of scar tissue within the lungs in the absence of any known cause. "ZFP36 deficiency upregulated CREBBP, enhanced I/R-induced lung injury, apoptosis, and inflammation, and increased I/R-induced lung fibrosis." (PMID 34238924, 2021). "Analysis of lung tissues in ZFP36-knockdown mice by Western blotting, immunohistochemistry, and real-time PCR showed that ZFP36 deficiency upregulated CREBBP, enhanced I/R-induced lung injury, apoptosis, and inflammation, and increased I/R-induced lung fibrosis." (PMID 34238924, 2021).
Infertility (2 papers, 2022 to 2024). "This search revealed that in the case of NANOS1 overexpression, three infertility related genes (CREBBP, CCNB1, and NPAS2) and five cancer-germ cell genes (CENPL, ERCC6L, KIF18A, SIAH1, and TRIM71) were present in three clusters." (PMID 35743036, 2022).
liver cancer (2 papers, 2020 to 2025). An epithelial or non-epithelial malignant neoplasm that arises from the liver. "Taken together, pifithrin-μ suppresses CREB1/CREBBP complex formation, CREB1-mediated transcription, and sorafenib resistance of mTOR-activated liver cancer cells." (PMID 39863613, 2025).
lymphoid neoplasm (2 papers, 2016 to 2025). A neoplasm composed of a lymphocytic cell population which is usually malignant (clonal) by molecular genetic and/or immunophenotypic analysis. "In addition, in the current study, we report for the first time recurrent mutations (5-10%) in CMML in the genes CREBBP, KMT2D and UMODL1, which have been previously reported in lymphoid neoplasms or solid tumors." (PMID 27486981, 2016).
MALT lymphoma (2 papers, 2021). An indolent, extranodal type of non-Hodgkin lymphoma composed of small B-lymphocytes (centrocyte-like cells). "In fact, as previously discussed, mutations in CREBBP are found in 4–22% of MALT lymphomas." (PMID 35008340, 2021). "Inactivation of chromatin remodeling genes are frequently observed in MALT lymphomas, with the most common mutated genes being TET2, KMT2D, CREBBP, TBL1X1, KMT2C, MT2C, EP300, among others." (PMID 35008340, 2021). "Several chromatin remodeling and transcriptional regulators are recurrently mutated in MALT lymphoma of different sites, including TBL1XR1, TET2, MLL2/KMT2D and CREBBP." (PMID 35008340, 2021). "In MALT lymphomas, mutations of TNFAIP3 and CREBBP (22% vs. 8%) are more frequent than in SMZLs." (PMID 34590593, 2021). "This suggests that epigenetic modulation of immune response with HDAC3 inhibitors (or EZH2 inhibitors) may be explored in CREBBP-mutant MALT lymphomas, alone or in combination with PD1/PD-L1 blockade (to prevent interferon-induced adaptive immune suppression)." (PMID 35008340, 2021). "In OAMZL, the most commonly reported epigenetic mutated gene is KMT2D with frequencies varying from 14% to 22%, and in Helicobacter pylori-negative gastric MALT lymphoma, KMT2D (17%) and CREBBP (14%) are the two most epigenetic regulator gene mutations." (PMID 35008340, 2021).
myeloid malignancies (2 papers, 2016 to 2025). "While CREBBP/EP300 gene mutations have been described in association with myeloid neoplasms." (PMID 39969535, 2025).
neuroendocrine tumors (2 papers, 2020 to 2021). "Furthermore, we observe distinct drivers which are enriched in somatic aberrations in pancreatic (MEN1, ATRX, DAXX, DMD and CREBBP) and midgut-derived neuroendocrine tumors (CDKN1B)." (PMID 34326338, 2021).
ossifying fibromyxoid tumor (2 papers, 2020). A rare soft tissue tumor of uncertain lineage characterized by the presence of neoplastic spindle to round cells forming cords in a fibromyxoid stroma. "A fusion involving CREBBP with BCORL1 has been described in ossifying fibromyxoid tumors, with a similar breakpoint region to that seen in our case, though with a distinct predicted fusion transcript that preserves the HAT domain of CREBBP." (PMID 32493417, 2020). "The CREBBP-BCOR fusion may be functionally related to the CREBBP-BCORL1 recently described in two cases of ossifying fibromyxoid tumors, a tumor type that shares fusion genes similar to those of ESS." (PMID 32933053, 2020).
preeclampsia (2 papers, 2015 to 2016). Preeclampsia is a hypertensive disorder of pregnancy that is characterized by new-onset hypertension with proteinuria presenting after 20 weeks of gestation, and depending on mild or severe forms may initially present with severe headache, visual disturbances, and hyperreflexia. "Maternal preeclampsia was reported for three patients with CREBBP mutations and one patient with EP300 mutation." (PMID 26788536, 2016). "CREBBP interacts with several proteins well known to be associated with preeclampsia, such as NFE2L2, LEP and VEGF/FLT1, but also with proteins not-yet related to preeclampsia." (PMID 26171964, 2015). "Preeclampsia was reported in mothers of RTS patients with both CREBBP and EP300 mutations." (PMID 26788536, 2016). "The 388-gene preeclampsia meta-signature offers a vital starting point for further studies into the relevance of these genes (in particular CREBBP/EP300) and their concomitant pathways as biomarkers or functional molecules in preeclampsia." (PMID 26171964, 2015). "Even when using a rather conservative approach, a protein-protein interaction network within our preeclampsia meta-signature emerges with CREBBP as key protein within this network." (PMID 26171964, 2015). "Even though CREBBP/EP300 were not identified as DEGs in the other two published meta-analyses, their involvement in preeclampsia was suggested based on association with differentially expressed transcription factors by Vaiman and colleagues." (PMID 26171964, 2015).
spina bifida (2 papers, 2010 to 2019). A congenital neural tube defect in which vertebrae are not fully formed. "A case–control study, including 297 spina bifida cases and 300 controls, found 37 SNPs within EP300 and CREBBP were associated with the occurrence of spina bifida." (PMID 31612645, 2019). "The purpose of this study is to evaluate the potential association between variations among human CITED2, CREBBP, EP300, TFAP2A, CARM1 and ALX1 genes and the risk for spina bifida." (PMID 20932315, 2010). "We have observed modest associations with risk of spina bifida in CITED2, EP300, CREBBP, TFAP2A and CARM1 genes but not ALX1 gene." (PMID 20932315, 2010).
squamous cell carcinoma (2 papers, 2021 to 2023). A carcinoma arising from squamous epithelial cells. "Additionally, mutations in CREBBP/EP300 are associated with recurrence following radiation in squamous cell carcinoma cohorts." (PMID 34732714, 2021).
Stroke (2 papers, 2021 to 2023). Sudden impairment of blood flow to a part of the brain due to occlusion or rupture of an artery to the brain. "CREBBP, NFE2L2 and PARP1 are known for their roles in the pathogenesis of stroke and post-stroke neurovascular remodeling and functional recovery." (PMID 34992531, 2021).
tongue cancer (2 papers, 2023 to 2025). A malignant neoplasm affecting the tongue. "The evidence from genomic analysis of tongue carcinoma has uncovered CREBBP mutation which is in line with our results." (PMID 40457841, 2025). "On the other hand, the PRI-724 inhibitor of the β-catenin–CREBBP interaction was the most effective in reducing glucose uptake and lactate release in the same tongue cancer cell lines." (PMID 38132445, 2023).
Type 2 diabetes (2 papers, 2013 to 2024). "Our study also revealed that CREB binding protein (CREBBP) and cardiotrophin-1 (CTF1) have suggestive roles in linking Type 2 diabetes and neuromuscular diseases." (PMID 23776558, 2013).
aggressive NK-cell leukemia (1 paper, 2023). A rare, highly aggressive, Epstein-Barr virus-associated leukemia, also known as aggressive NK-cell leukemia/lymphoma; it may represent the leukemic counterpart of nasal type extranodal NK/T-cell lymphomas. "For example, CREBBP/EP300 mutations frequently occur in primary and relapsed pediatric ALL, aggressive NK-cell leukemia (ANKL), and chronic-phase chronic myeloid leukemia (CML-CP)." (PMID 36831561, 2023).
anemia (1 paper, 2022). A reduction in the number of red blood cells, the amount of hemoglobin, and/or the volume of packed red blood cells. "The central nodes of the top gene clusters for AAomax were complete embryonic lethality during organogenesis, response to nutrient levels and circulatory system processes, for AAomin the CREBBP PPI subnetwork, smooth muscle cell proliferation and anemia." (PMID 34968759, 2022).
aortic valve disease (1 paper, 2022). "Notably, expression levels of CREBBP are reduced in valve leaflets from patients with aortic valve disease (n = 4) compared to healthy patient leaflets (n = 5)." (PMID 36176599, 2022).
Azoospermia (1 paper, 2016). Absence of any measurable level of sperm,whereby spermatozoa cannot be observed even after centrifugation of the semen pellet. "We also identified new candidate genes, CREBBP and BCAR1, which may play a role in azoospermia." (PMID 27834916, 2016).
B-cell acute lymphoblastic leukemia (1 paper, 2025). A neoplasm of lymphoblasts committed to the B-cell lineage, typically composed of small to medium-sized blast cells. "CREBBP mutations in B-cell acute lymphoblastic leukemia (B-ALL) are linked to poor prognosis and chemoresistance." (PMID 40393984, 2025).
B-cell neoplasm (1 paper, 2025). A group of heterogeneous lymphoid tumors generally expressing one or more B-cell antigens or representing malignant transformations of B-lymphocytes. "In the murine B-cell neoplasms example, the cases with chromatin-modifying gene CREBBP or EP300 mutations that had a decreased H3K27 acetylation led to higher M2 polarization and a faster tumor progression when compared to CREBBP/EP300 wild-type, regulated via the FBXW7-NOTCH-CCL2/CSF1 axis." (PMID 40426926, 2025).
benign brain tumors (1 paper, 2024). "In our two-sample MR study, CREBBP affected benign brain tumors." (PMID 39043735, 2024).
bladder (1 paper, 2025). "We observed a strong negative association between KDM6A‐mut signature score and other aberrations associated with bladder patients with PD‐L1 responders, and a strong positive correlation with CREBBP‐mut and EP300‐mut scores." (PMID 40693457, 2025).
breast NETs (1 paper, 2022). "Lysine acetyltransferase CREBBP was mutated in 11% of breast NETs, which is of a similar magnitude to that reported previously in neuroendocrine small-cell lung cancer." (PMID 36085291, 2022). "This study may lay the foundation for future studies evaluating potential therapeutic breast NET targets, such as CREBBP." (PMID 36085291, 2022).
cardiac septal defect (1 paper, 2009). "Of these, 3 genes (SRF, EP300, and CREBBP) have been associated with cardiac septal defect." (PMID 19245720, 2009).
cerebral infarction (1 paper, 2025). An ischemic condition of the brain, producing a persistent focal neurological deficit in the area of distribution of the cerebral arteries. "Through bioinformatics analysis, we identified key targets associated with cellular senescence and circadian rhythm in cerebral infarction, specifically CREBBP, FOS, CDK4, MMP9, PTEN, and HIF1A." (PMID 40629591, 2025).
cervical squamous cell carcinoma (1 paper, 2017). A squamous cell carcinoma arising from the cervical epithelium. "This implies that somatic alterations in TGFBR2, CREBBP, and SMAD4 may be cervical squamous cell carcinoma-specific, although E7-driven expression effects in the TGFβ pathway may still play a role in carcinogenesis in other HPV-positive cancers." (PMID 28771191, 2017).
cervix (1 paper, 2021). "We found that CREBBP/EP300 mutations were associated with poorer overall survival in radiation-treated patients with lung and cervix squamous tumors." (PMID 34732714, 2021).